ATR (ATR checkpoint kinase)
Diseases named in the same sentence as ATR in open-access papers (continued):
Sharing a sentence is not in itself a finding about the gene and the disease.
breast cancer (continued). "To test this hypothesis, we inhibited DNA2 with the specific DNA2 inhibitor C5 and/or blocked ATR activation with the ATR inhibitor VE‐821 in several commonly used aggressive cancers cell lines such as MCF7 (breast cancer), and HCT‐116 (colorectal cancer) and H460 (non‐small‐cell lung cancer)." (PMID 29773570, 2018). "For this purpose, the complete sequence of the 47 exons and flanking intronic sequences of the ATR gene were analyzed in DNA samples from individuals affected with breast cancer from non-related BRCA1- and BRCA2-negative high-risk French Canadian breast/ovarian families." (PMID 17010193, 2006). "In breast cancer models, BAK acts as a selective phytoestrogen, induces S-phase arrest, activates the ATM/ATR-Chk1/Chk2 axis, and triggers mitochondrial apoptosis, particularly in ERα-positive cells." (PMID 41594634, 2026). "Currently, two ATR inhibitors—Ceralasertib (AZD6738) and Berzosertib (VX-970, M6620)—are under clinical evaluation for breast cancer treatment." (PMID 40949156, 2025). "Currently, a variety of cell cycle checkpoint kinase inhibitors are also under research and their anti-tumor effects in combination with PARP inhibitors are evaluated, including inhibition of CHEK1/2, ATM, ATR, and WEE1 in breast cancer." (PMID 39334297, 2024). "Our previous studies have shown that CPX can inhibit cell proliferation and apoptosis in rhabdomyosarcoma (Rh30) and breast cancer (MDA-MB-231) cells; meanwhile, CPX can induce DNA damage, which activates the ATR-Chk1 DDR pathway." (PMID 39513859, 2024). "We found that CHEK2 is the only cell cycle checkpoint kinase gene that is more likely to be mutated in the germ line than somatically (threefold enrichment in ER+/HER2− breast cancer relative to ATM and >50-fold enrichment relative to ATR, P = 3.7 × 10−12)." (PMID 37390209, 2023). "In contrast, CHK1 has been known to autonomously transduce the ATR‐mediated RSR pathway, and nuclear pCHK1 levels have been shown to predict early local recurrence and shorter survival in breast cancer patients." (PMID 36373784, 2023). "Breast cancer cells with higher RNF126 expression have CDK2-mediated replication stress, which makes them potential targets for ATR inhibitors." (PMID 36539893, 2022). "MCM10 OE was able to increase RPA2 compared to controls in breast cancer patient biopsy and in MCF10A OE cells, which further induced high expression of downstream proteins ATR and CHEK1, supporting the possibility of increased ssDNA in MCM10 OE cells." (PMID 35813483, 2022). "ATR and CHK1 inhibitors synergize with compounds that induce replication stress in breast cancers, including nucleoside analogues, platinum-based agents, and PARP inhibitors." (PMID 36359297, 2022). "This study explores the relationship between the E3 ubiquitin ligase Ring finger protein 126 (RNF126) and early breast cancer metastasis and tests the hypothesis that RNF126 determines the efficacy of inhibitors targeting Ataxia telangiectasia mutated and Rad3-related kinase (ATR)." (PMID 36539893, 2022). "Pan-HDAC inhibitors panobinostat and vorinostat hyperacetylate nuclear HSP90, which degrades DNA repair machinery proteins BRCA1, ATR, and CHK1 in breast cancer cells." (PMID 34696786, 2021). "Pan-HDAC inhibitors panobinostat and vorinostat hyperacetylate nuclear HSP90, resulting in proteasomal degradation of DNA repair machinery proteins BRCA1, ATR, and CHK1 in breast cancer cells." (PMID 34696786, 2021).
breast cancer (continued). "Pan-HDAC inhibitors panobinostat and vorinostat/suberoylanilide hydroxamic acid (SAHA) cause hyperacetylation of nuclear HSP90, degrading DNA repair machinery proteins BRCA1, ATR, and CHK1 in breast cancer cells." (PMID 34696786, 2021). "Consistently, analysis of human breast cancer tissue demonstrates NOTCH1 is highly expressed in TNBCs, and the activated form of NOTCH1 correlates positively with increased phosphorylation of ATR." (PMID 32591500, 2020). "Other ATR inhibitors, schisandrin B and KU60019, presented promising anti-tumor properties in vitro and partly in vivo in luminal A breast cancer models, however, they have a limited clinical use due to a poor bioavailability." (PMID 32947901, 2020). "Immunoblotting as well as quantitative RT-PCR were utilized to show the role of breast cancer cells and IL-6 as well as AUF-1 in downregulating ATR in breast stromal fibroblasts." (PMID 32414408, 2020). "We investigated ATM, ATR and MYC at the transcriptional level [Molecular Taxonomy of Breast Cancer International Consortium cohort (n = 1950)] and at the protein level in the Nottingham series comprising 1650 breast tumours." (PMID 30746633, 2019). "In conclusion, we provide strong clinical evidence that ATM signalling and ATR signalling can influence clinicopathological features and survival outcomes in patients with MYC overexpressed breast cancer." (PMID 30746633, 2019). "We show that ATM and ATR levels have clinicopathological, predictive and prognostic significance in MYC overexpressed breast cancer." (PMID 30746633, 2019). "We then proceeded to investigate MYC, ATR and ATM protein levels in clinical breast carcinoma samples." (PMID 30746633, 2019). "We now show that kinases ATR, CHK1 and WEE1 when silenced confer sensitivity to cisplatin of multiple basal type breast cancer cells and cisplatin resistant MB-MDA-231 breast cancer cells." (PMID 28262781, 2017). "Consistent with this, treatment with an HSP90 inhibitor was shown to degrade and deplete expression of BRCA1, ATR and CHK1, resulting in impairment of the DDR and DNA repair, which sensitized breast cancer cells to DNA damage." (PMID 25026298, 2014). "ATR and CHEK1 tagSNPs were genotyped in the Sheffield Breast Cancer Study (SBCS; 1011 cases and 1024 controls) using Illumina GoldenGate assays." (PMID 23844225, 2013). "ATM and ATR become active and phosphorylate CHK1 and CHK2, which then trigger signaling pathways that result in either cell cycle arrest or apoptosis, thereby impeding the advancement of breast cancer." (PMID 40612872, 2025). "A total of 18 cancer genes including ERBB2/HER2, ATR, ESR1 and MAP3K1 were identified to be LateN-to-EarlyT replicated in BRCA and affected by an APOBEC3-mediated omikli event in at least one tumour in the breast cancer cohort." (PMID 39019871, 2024). "Unlike mutations in ATM or CHEK2, mutations in ATR alone are uncommon in both primary and metastatic ER+/HER2− breast cancer." (PMID 37390209, 2023). "The combination of ATR and WEE1 inhibitors were also found to have tumor-selective synthetic lethality, leading to tumor remission and inhibited metastasis with minimal side effects in an orthotopic breast cancer model." (PMID 36378528, 2023). "Furthermore, other recent studies have illustrated how key RSR members including ATR, CHK1, and DNA-PK regulate immune response in breast cancer." (PMID 36359297, 2022).
breast cancer (continued). "In brief, our results suggest that higher expression of RNF126 may accelerate breast cancer metastasis and that RNF126 may be an effective biological target for ATR inhibitors." (PMID 36539893, 2022). "Hence, this study aimed to evaluate the radiosensitizing ability under fractionation of ATM inhibitor AZD0156, ATR inhibitor AZD6738 and PARP inhibitor AZD2281 (olaparib), utilizing MDA-MB-231 and MCF-7 human breast cancer cells." (PMID 35954456, 2022). "We demonstrated that breast cancer cells with higher RNF126 expression could stall the replication fork and trigger abnormal replication initiation after ATR inhibitor application." (PMID 36539893, 2022). "Our knockdown experiments suggest that the ATM/CHK2 axis is likely necessary for mediating BQ expression in TAM-resistant breast cancer cells, whilst that of ATR and CHK1 is not." (PMID 36293165, 2022). "After using CDKs inhibitors to pretreat breast cancer cells with a higher level of RNF126, we observed that the cell-killing effect of ATR inhibitors could be counteracted by the inhibitors, in conjunction with an alleviates replication stress." (PMID 36539893, 2022). "As well as paclitaxel, BAY-1816031 exhibits promising anti-proliferative activity against cancer cell lines when combined with ATR or PARP inhibitors and significantly reduces tumour size in breast cancer xenografts when combined with the PARP inhibitor olaparib." (PMID 34925867, 2021). "(D) Box-plots of HR (BRCA1, BRCA2, ATR) and NHEJ (PRKDC, XRCC5, XRCC6) protein expression levels (ratio to pool) in the different groups of breast cancer cell lines according to AZD1775 response characteristics (recovering-basal, sensitive-basal and recovering-luminal)." (PMID 32628111, 2020). "We conclude that ATR/ATM-directed stratification and personalisation of therapy may be feasible in MYC overexpressed breast cancer." (PMID 30746633, 2019). "Although MYC amplification promotes aggressive breast cancer phenotype, whether ATR and ATM expressions influence pathology and clinical outcomes in MYC overexpressed breast cancers is unknown." (PMID 30746633, 2019). "The non-cell-autonomous ATR-related enhancement of the migration/invasion abilities of breast cancer cells was mediated in an SDF-1/IL-6-dependent manner." (PMID 30410668, 2018). "Herein we investigated the ATR-Chk1 and ATM-Chk2 signalings in male breast cancer (MBC)." (PMID 28808232, 2017). "We performed immunohistochemical analysis on sections from formalin-fixed, paraffin-embedded material from a clinical cohort of breast carcinomas and adjacent normal breast tissue with antibodies against γH2AX and phosphorylated RPA (RPA-P), markers of DNA damage and ATR signalling, respectively." (PMID 27634334, 2016). "We conclude that common alleles of ATR and CHEK1 are not implicated in breast cancer risk or survival, but we cannot exclude effects of rare alleles and of common alleles with very small effect sizes." (PMID 23844225, 2013). "Interestingly, although we have previously reported that RNF126 knockdown reduces CHEK1 expression, we did not observe a synergistic lethal effect of ATR inhibitors on breast cancer cells with knockdown of RNF126." (PMID 36539893, 2022). "Furthermore, we have recently shown that ATR-negative CAFs predict a poor OS as well as DFS for breast cancer patients." (PMID 35821051, 2022). "The results showed that RNF126 knockdown increased p-ATR expression, which meant that the function of ATR protein had been activated, but ATR inhibitors could not effectively kill breast cancer cells with RNF126 knockdown." (PMID 36539893, 2022). "In this work, we performed an in silico analysis of transcriptomic datasets in breast cancer, and focused on those involved in DNA damage, as were clearly upregulated using gene set enrichment analyses (GSEA), particular the following pathways: ATM/ATR, BARD1 and Fanconi Anemia." (PMID 33925616, 2021).
breast cancer (continued). "The treatment of breast cancer cell lines (MCF7 and SkBr3) and colon cancer cell line (HCT-116) with the IC50 and twice the IC50 of SIMR1281 for 24 h increased the level of γ-H2Ax and p-ATM, while a minimal effect was detected in the phosphorylation level of ATR." (PMID 34200264, 2021). "For breast cancer patients, our data underscore that overexpression of nuclear and/or cytoplasmic Cyclin E could be used as a selection criterion for treatment with drugs that target replication stress, including inhibitors of WEE1 and ATR." (PMID 32964114, 2020). "However, we conclude there is little evidence to support any role for common SNPs in the ATR and CHEK1 regions in breast cancer risk or survival." (PMID 23844225, 2013). "First, we reveal that AEP accumulates in ductal breast carcinoma cells from nonresponder patients, resulting in reduced ATR nuclear levels, with these patients showing a higher AEP/ATR ratio." (PMID 40012043, 2025). "Nonetheless, our results showed that RNF126-depleted breast cancer cells were not sensitive to CHEK1 and ATR inhibitors." (PMID 36539893, 2022). "We previously found no additivity/synergy between xentuzumab and ATR inhibition in MCF7, and confirm here that ATR inhibition was not a hit in any of the 5 screened breast cancer cell lines, while in contrast we find evidence of synergy with CHK1 inhibition." (PMID 34773074, 2022). "Newer ATR inhibitors with better pharmacological properties (such as M6620, AZD6738 and BAY1895344) have not been tested for luminal A breast cancer yet." (PMID 32947901, 2020).
ovarian carcinoma (99 papers, 2005 to 2026). A malignant neoplasm originating from the surface ovarian epithelium. "In this study, damaging ATR variants were found in pancreatic, breast and ovarian cancer in one patient each." (PMID 38184614, 2024). "For example, PARP inhibitors sensitize ovarian cancer cells to ferroptosis by synergistically activating ATM/ATR and causing DNA damage." (PMID 37842240, 2023). "As polβ-deficient ovarian cancer cells are not only sensitive to platinum treatment but also show features of replication stress as evidenced by accumulation of ATR and pChk1ser 345, we tested a synthetic lethality application for either PARPi or PARGi." (PMID 33674744, 2021). "High ATR expression in ovarian cancer tissues has been linked with poor survival and progression free-survival, while it has been identified among the critical factors in determining platinum sensitivity in cell lines models." (PMID 32512900, 2020). "Pre-clinical work has identified ARID1A deficiency as a biomarker for the efficacy of ATR inhibitors, and in ovarian cancer cells, the multi-kinase inhibitor dasatinib." (PMID 30763338, 2019). "We found that Ribociclib treatment was associated with a decrease in p-Chk1 in all tested ovarian cancer cells and in ATR in the Hey1 cell line." (PMID 29644000, 2018). "One case in our study displayed pathogenic ATR mutation, while the upregulation of the ATR pathway may play a role in resistance to PARP inhibitors in ovarian cancer cell lines." (PMID 38542259, 2024). "Patient-derived xenograft models of BRCA-wildtype and CCNE1-amplified platinum-resistant ovarian cancer, which are associated with increased baseline activation of ATR/CHK1, demonstrated tumor reduction and a significant increase in OS when treated with the combination of PARPi and ATRi." (PMID 38894867, 2024). "For example, one study showed that ATR inhibitor in combination with olaparib promoted greater activity than did olaparib monotherapy via mitotic catastrophe-induced cell death in BRCA2-mutated ovarian cancer." (PMID 38069409, 2023). "Defects in NHEJ have also been implicated in ovarian cancer, and linked to ATR inhibitor response." (PMID 35954206, 2022). "Preclinical observations indicate that the synthetic lethality of ATR or CHK1 inhibitors in ATM-deficient cancers may be a new opportunity for effective ovarian cancer therapy." (PMID 32316968, 2020). "Importantly, depletion or inhibition of Rad51 dramatically increased the sensitivity of ovarian cancer cells to ATR and Chk1 inhibition, suggesting that HR deficiency and inhibition of ATR/Chk1 pathway can be synthetically lethal." (PMID 26295265, 2015). "Similarly, pharmacological inhibition of ATR using VE-821 induced greater sensitivity to veliparib in BRCA1-deficient ovarian cancer cell lines." (PMID 25124282, 2014). "Based on its central role in the maintenance of genomic integrity, we hypothesized that germline mutations in ATR may account for some breast and/or ovarian cancer families." (PMID 15987455, 2005). "Based on this, we wanted to determine whether ATR germline mutations are involved in susceptibility to breast and/or ovarian cancer, and conducted a mutation analysis of all 47 coding exons and exon–intron boundaries in the affected index cases in 126 families." (PMID 15987455, 2005). "For example, chemokine CXCL2 maintains cancer cell stemness and activates the ATR/CHK1 signaling pathway to promote platinum resistance in ovarian cancer." (PMID 40968783, 2026). "The success in NSCLC and ovarian cancer subgroups underscores that ATR inhibitors must be developed as a biomarker-driven therapy." (PMID 41409249, 2025).